ENPP1 (ectonucleotide pyrophosphatase/phosphodiesterase 1)
Diseases named in the same sentence as ENPP1 in open-access papers (continued):
Sharing a sentence is not in itself a finding about the gene and the disease.
COVID-19 (2 papers, 2021 to 2022). A disease caused by infection with severe acute respiratory syndrome coronavirus 2. "The univariate Cox analysis highlighted that 7 genes (including MRC1, CP, ITGA5, SNCA, HARS1, ENPP1, and PLAU) were significantly (p < 0.05) associated with CHOL/COVID-19." (PMID 34176789, 2021). "There is a significant reduction in the expression of ENPP1, ENPP2, ENPP3, and NT5E in the blood of patients with severe COVID-19 when compared to HDs and a lower expression of ENPP2 and ENPP3 when compared to mild hospitalized cases." (PMID 36248842, 2022). "Herein, we detected the gene expression of ENPP1, ENPP2, ENPP3, ENTPD1 (CD39), ENTPD5, and NT5E (CD73) in the whole blood of COVID-19 patients." (PMID 36248842, 2022). "As per the independent prognostic and survival analyses, few of the important differentially expressed genes, including MRC1, CP, ITGA5, SNCA, HARS1, ENPP1, and PLAU may function as potent biomarkers for screening and characterizing different stages of CHOL patients with COVID-19." (PMID 34176789, 2021).
craniosynostosis (2 papers, 2019 to 2022). Craniosynostosis is defined as the premature fusion of one or more cranial sutures leading to secondary distortion of skull shape resulting in skull deformities with a variable presentation. "In contrast, the incidence of craniosynostosis was significantly diminished only upon homozygous deletion of ENPP1 in TNAP null mice." (PMID 35909501, 2022). "Results show that homozygous deletion of ENPP1 significantly diminishes the incidence of craniosynostosis and that skull shape abnormalities are rescued by hemi- or homozygous deletion of ENPP1 in TNAP null mice." (PMID 35909501, 2022). "Together, our results demonstrate that balanced expression of TNAP and ENPP1 enzymes are essential for microstructure and mineralization of both skull and long bones, and for preventing craniosynostosis." (PMID 35909501, 2022). "The incidence of craniosynostosis was significantly higher in TNAP−/−/ENPP1+/+ mice than in TNAP−/−/ENPP1−/− mice, but not when compared to TNAP−/−/ENPP1+/− mice." (PMID 35909501, 2022).
diabetic kidney disease (2 papers, 2015 to 2021). Progressive kidney disorder caused by vascular damage to the glomerular capillaries, in patients with diabetes mellitus. "A meta-analysis in Asian and European populations revealed that the K121Q SNP of the ENPP1 gene was associated with an increased susceptibility to diabetic kidney disease." (PMID 34208364, 2021). "The potential association between the K121Q (A/C, rs1044498) polymorphism in the ectonucleotide pyrophosphatase/phosphodiesterase (ENPP1) gene and risk of diabetic kidney disease (DKD) has been investigated." (PMID 25794151, 2015). "Pooled measures for association between the ENPP1 K121Q polymorphism and susceptibility to diabetic kidney disease." (PMID 25794151, 2015).
fatty liver (2 papers, 2015 to 2025). "Altogether, the present findings suggest that hepatic Enpp1 deficiency exacerbated hepatic steatosis progression." (PMID 39972484, 2025). "Currently, the role of Enpp1, a key protein closely associated with MAFLD progression, in the hepatic steatosis and metabolic dysregulation of MAFLD is not well understood." (PMID 39972484, 2025). "Histochemical analysis based on H&E and Oil red O staining revealed that Enpp1 overexpression reduced hepatic steatosis, which was consistent with the reduction in liver TG levels, liver T-CHO levels and serum TG levels in Enpp1-overexpressed HFD-fed mice." (PMID 39972484, 2025). "Common SNPs in ENPP1 and ABCC2 have suggestive association with fatty liver, but with less compelling significance." (PMID 26740948, 2015). "Additionally, we observed that HFD fed liver-specific Enpp1 knockout (CKO) mice had significantly worse hepatic steatosis, wheres specific those with liver-specific overexpression of Enpp1 had reduced liver lipid accumulation." (PMID 39972484, 2025). "Furthermore, we established liver-conditional knockout of Enpp1 (CKO) mice to elucidate the effect of Enpp1 on hepatic steatosis." (PMID 39972484, 2025). "To determine the effect of Enpp1 on hepatic steatosis and metabolic dysregulation in MAFLD, we developed liver-specific knockout of Enpp1 (CKO) mice Enpp1 and liver-specific overexpression of Enpp1 mice." (PMID 39972484, 2025).
monocytic leukemia (2 papers, 2018). "Moreover, the wild-type ENPP1, but not the S514L mutant, suppressed the IFN-β induction, the downstream consequence of STING signaling in human monocytic leukemia THP-1 cell line, highlighting the biological importance of the G-pocket for the negative regulation of the STING signaling." (PMID 30356045, 2018).
otitis media (2 papers, 2016 to 2019). Inflammation of the anatomical structures of the middle ear, which is most often caused by an infectious process. "In this study, researchers examined mice with a point mutation in the Enpp1 gene, which resulted in a high incidence of otitis media." (PMID 31915695, 2019). "Here, we report on otitis media-related hearing loss in asj (ages with stiffened joints) mutant mice, which bear a point mutation in the Enpp1 gene." (PMID 27959908, 2016). "ENPP1 deficiency is known to cause elevated serum levels of FGF23 in Enpp1 mutant mice, and excess FGF23 secreted in the middle ear may trigger mucoperiosteum proliferation, which may contribute to the development of otitis media." (PMID 27959908, 2016).
schizophrenia (2 papers, 2020 to 2021). A major psychotic disorder characterized by abnormalities in the perception or expression of reality. "Another of the candidate genes ENPP1 has been linked to learning and memory abilities in mice, while MAP7 has been shown to play a critical role in the developmental regulation of neural axon branch maturation (MAP7,) and is also involved in schizophrenia (MAP7,)." (PMID 33138119, 2020).
serous ovarian carcinoma (2 papers, 2021 to 2022). "Relationship between ENPP1 protein expression, prognostic parameters and chemosensitivity in high-grade serous ovarian carcinoma." (PMID 33635867, 2021). "We stratified the relationship between prognostic parameters, chemosensitivity and ENPP1 expression in patients with high-grade serous ovarian carcinoma." (PMID 33635867, 2021). "Expression of ENPP1 protein in normal ovarian tissue, ovarian serous cystadenoma and high-grade serous ovarian carcinoma." (PMID 33635867, 2021). "The results showed that the expression of ENPP1 was significantly increased in high-grade ovarian serous carcinoma, the number of strong expression was 85.4% (22.3%+63.1%) and only 1.03% (1.03%+0.0%) in serous cystadenoma, but no in normal ovarian epithelium (P< 0.05)." (PMID 33635867, 2021).
triple-negative breast carcinoma (2 papers, 2022 to 2025). An invasive breast carcinoma which is negative for expression of estrogen receptor (ER), progesterone receptor (PR), and human epidermal growth factor receptor 2 (HER2). "The ATP-hydrolytic ectoenzyme ENPP1 has been implicated in the metastasis and recurrence in triple-negative breast cancer (TNBC), primarily by contributing to tumor cell survival and treatment resistance." (PMID 40506449, 2025).
viral infection (2 papers, 2015 to 2022). "ENPP1 inhibitors, and perhaps even cGAMP-specific ENPP1 inhibitors, may be therapeutically beneficial during viral infection, while administering recombinant ENPP1 or blocking cGAMP import may reduce extracellular cGAMP-associated inflammation." (PMID 35588451, 2022). "We uncover that ENPP1's degradation of extracellular cGAMP has a long evolutionary history, and that this mechanism is critical for controlling diverse immune threats, including viral infection and inflammation." (PMID 35588451, 2022). "Since ENPP1 only regulates the extracellular cGAMP branch of STING signaling, it is unclear if the Enpp1H362A mice would be more resistant to viral infection." (PMID 35588451, 2022). "Despite PDE12, ENPP1 and AKAP7 degrades 2′-5′ oligoadenylates in vitro their importance during viral infection, has yet to be reported." (PMID 26113370, 2015).
Zinc deficiency (2 papers, 2018 to 2021). A deficiency of the essential metal Zinc; an essential cofactor for many enzymes. "Zinc deficiency severely impairs the activities of major ectoenzymes (ENPP1, ENPP3, NT5E/CD73, and TNAP), and also strongly suppresses adenine-nucleotide hydrolysis in cell-membrane preparations or rat plasma, thereby increasing ATP and ADP levels and decreasing adenosine levels." (PMID 30271993, 2018). "For example, both high expression of TNAP, ENPP1, ENPP3, and NT5E/CD73 and low expression of ENTPD1/CD39 increase the susceptibility of cells to the effects of zinc deficiency on extracellular adenine-nucleotide metabolism." (PMID 30271993, 2018). "The quantification of each adenine nucleotide and adenosine hydrolyzed from ATP revealed that the effects of zinc deficiency varied depending on the cell type, which can be attributed to the distinct expression pattern and level of ENTPD1/CD39, ENPP1, ENPP3, NT5E/CD73, TNAP, PAP, and their isozymes." (PMID 30271993, 2018).
acromegaly (1 paper, 2023). Acromegaly is an acquired disorder related to excessive production of growth hormone (GH) and characterized by progressive somatic disfigurement (mainly involving the face and extremities) and systemic manifestations. "Thus, acromegaly and the associated genes may be categorized as a relatively strong factors equivalent to heterozygous ENPP1 deficiency." (PMID 37530996, 2023).
acute coronary syndrome (1 paper, 2018). Signs and symptoms related to acute ischemia of the myocardium secondary to coronary artery disease. "Additionally, we detected that ENPP1 K121Q was related to the risk of MI, CAD, and acute coronary syndrome (ACS) in the dominant model (all P < .05)." (PMID 29979387, 2018).
Anxiety (1 paper, 2022). Intense feelings of nervousness, tension, or panic often arise in response to interpersonal stresses. "The highest reported burden for children with ENPP1 Deficiency was self-care related to management of treatments, followed by physical health related to hearing loss, mental health due to stress/anxiety, and physical health related to bone and joint pain." (PMID 35895733, 2022). "It is easy to anticipate the burden of hospitalization and management of medications as well as anxiety and stress contribute to poor emotional function in the younger children with ENPP1 Deficiency." (PMID 35895733, 2022). "As patients with ENPP1 Deficiency grew older there was a shift in the symptoms, as these patients also face hearing loss, bone/joint pain and stiffness, stress, and anxiety." (PMID 35895733, 2022).
aortic valve disease (1 paper, 2022). "The obtained caAcvr1:Nfatc1 mutants that were homozygous for Enpp1 (Enpp1−/−) died in utero, and thus could not be used to study the progression of aortic valve disease, while caAcvr2:Nfatc1:Enppi+/− mice were phenotypically indistinguishable from their caAcvr1:Nfatc1Cre littermates." (PMID 36005436, 2022).
asthma (1 paper, 2018). "Interestingly, it has been reported that the high amounts of ATP detected during asthma exacerbations could be due to reduced leukocyte expression of ectonucleotide pyrophosphatase/ phosphodiesterase 1 (ENPP1), another ATP degrading enzyme." (PMID 29807526, 2018).
astrocytoma (1 paper, 2023). "However, in the other group, TCGA astrocytoma, A2AR was negatively linked to HIF1, ENPP1, and pannexin, and positively correlated to ADK." (PMID 37047660, 2023). "However, in the other group, TCGA astrocytoma, A2AR was negatively related to HIF1a, ENPP1 (ectonucleotide pyrophosphatase/phosphodiesterase 1), and pannexin, and positively correlated with ADK (adenosine kinase)." (PMID 37047660, 2023).
bladder cancer (1 paper, 2023). "The expression of five of the eight GMII genes (TALDO1, AHCY, FASN, GALK1 and SLC7A9) in bladder cancer tissues was higher than that in normal tissues, while ENPP1, CYP19A1 and HSPG2 were down-regulated in tumor tissues (p < 0.05)." (PMID 36911676, 2023). "In this study, we established the GMII consisting of eight glutamine metabolism-related genes (ENPP1, GALK1, TALDO1, CYP19A1, FASN, AHCY, SLC7A9, and HSPG2), a high value of which is associated with poor prognosis in bladder cancer patients." (PMID 36911676, 2023).
breast invasive carcinoma (1 paper, 2023). "We observed similar increases in ENPP1 expression along the oncogenic trajectory from normal tissue to tumor-adjacent tissue to primary tumor in human breast invasive carcinoma (BRCA)." (PMID 38117852, 2023).
calcific aortic valve disease (1 paper, 2018). "In osteoblasts, ENPP1 generates PPi, which when hydrolyzed generates Pi with subsequent formation of hydroxyapatite, yet interestingly and similar to what was found in cardiac calcification, ENPP1 has also been found to be highly expressed in calcific aortic valve disease and in VICs." (PMID 29632866, 2018).
cystic fibrosis (1 paper, 2023). Autosomal recessive disorder caused by pathogenic variants in the CFTR gene (cystic fibrosis transmembrane conductance regulator), which encodes a chloride and bicarbonate channel expressed in epithelial cells, and follow the diagnosis criteria. "Exemplar cases include a patient with cystic fibrosis harbouring a novel exonic LINE1 insertion in CFTR and a patient with generalised arterial calcification of infancy with complex interlinked duplications involving exons 2–6 of ENPP1." (PMID 37558402, 2023).
Down syndrome (1 paper, 2024). "The patient has had two subsequent pregnancy terminations; one fetus was found to have a homozygous ENPP1 gene mutation, and the other displayed no ENPP1 mutation but was diagnosed with Down syndrome." (PMID 41001612, 2024).
ear malformation (1 paper, 2016). "FGF23-deficient mice show a mixed hearing loss and middle ear malformations, and changes in circulating FGF23 have been observed in humans and mice with ENPP1 and PHEX deficiencies." (PMID 27959908, 2016).
Ewing sarcoma (1 paper, 2025). A small round cell tumor that lacks morphologic, immunohistochemical, and electron microscopic evidence of neuroectodermal differentiation. "A more recent surfaceome analyses revealed many new Ewing sarcoma cell surface targets including ENPP1 and CDH11 in addition to known IL1RAP, STEAP1, ADGRG2 and CD99, providing newer cell surface targets for immunotherapeutic application in Ewing sarcoma." (PMID 40442778, 2025).
hyperostosis (1 paper, 2014). Excessive thickening of bone. "Conversely, Spp1 has been reported to be upregulated in spinal hyperostosis of twy mice, which represent another Enpp1 allele." (PMID 24906371, 2014).
hyperphosphatemia (1 paper, 2025). Abnormally high level of phosphate in the blood. "Similar increases in Ank and Enpp1 expression by mouse osteoblasts by extracellular Pi have been previously noted and may, along with decreased local phosphatase expression, contribute to the accumulation of unmineralised osteoid observed in Fgf23-deficient mice, despite a marked hyperphosphatemia." (PMID 40791815, 2025).
insulinoma (1 paper, 2018). "In that study, the expression level of ENPP1 protein in normal individuals was compared with that in insulinoma patients who were shown to have persistently high levels of endogenous insulin." (PMID 29513794, 2018). "There was no statistical difference in endogenous ENPP1 protein levels between insulinoma patients and healthy insulin-sensitive individuals." (PMID 29513794, 2018). "In addition, unlike the normal individuals, the endogenous ENPP1 protein levels were similar among insulinoma patients except in one case, consistent with our hypothesis of the suppressive effect of high level of endogenous insulin on Enpp1 expression in these patients." (PMID 29513794, 2018).
knee osteoarthritis (1 paper, 2023). "The deficiency of ectonucleotide pyrophosphatase/phosphodiesterase 1 (Enpp1) causes the phenotype similar to knee osteoarthritis (OA)." (PMID 37370114, 2023).
leukemia (1 paper, 2024). A malignant (clonal) hematologic disorder, involving hematopoietic stem cells and characterized by the presence of primitive or atypical myeloid or lymphoid cells in the bone marrow and the blood. "Among all cancers, leukemia cells express the lowest levels of ENPP1, which hydrolyzed cGAMP, allowing sustained cGAMP production in cancer cells." (PMID 38413714, 2024).
Liver cirrhosis (1 paper, 2022). "Liver cirrhosis with liver failure of any grade is associated with a deficit in plasma PPi, which is the result of a significant reduction in the gene expression levels of key regulators of PPi synthesis in the liver, i.e., ABCC6 and ENPP1, concomitant to enhanced degradation via TNAP." (PMID 35884801, 2022).
metastatic disease (1 paper, 2023). "Furthermore, patients with stage IV metastatic disease have significantly higher ENPP1 RNA expression than patients with stage III disease." (PMID 38117852, 2023).
nonimmune hydrops fetalis (1 paper, 2025). "Polyhydramnios and nonimmune hydrops fetalis may be linked to vascular dysfunction caused by ENPP1 Deficiency through potential increased central venous pressure, changes in oncotic pressure, and neurohormonal changes that may result in amniotic fluid accumulation." (PMID 40176950, 2025).
odontohypophosphatasia (1 paper, 2025). A particular form of hypophosphatasia (HPP) characterized by reduced activity of unfractionated serum alkaline phosphatase, premature exfoliation of primary and/or permanent teeth and/or severe dental caries, in the absence of skeletal system abnormalities. "It is not clear whether this ALPL loss-of-function variant is in keeping with HPP or odontohypophosphatasia, or the degree to which it may ameliorate the ENPP1 phenotype." (PMID 41445557, 2025).
plasmacytoma (1 paper, 2017). Plasmacytoma is a localized mass of neoplastic monoclonal plasma cells that represents approximately 5% of all plasma cell neoplasms. "Among the 12-member glucose transporter (GLUT) family, GLUT1 was the dominant transporter expressed by PCs as determined by RNAseq analyses of an ENPP1-deficient plasmacytoma cell line." (PMID 29259245, 2017).
psoriasis (1 paper, 2021). An autoimmune condition characterized by red, well-delineated plaques with silvery scales that are usually on the extensor surfaces and scalp. "Furthermore, genes encoding other PAR hydrolases were specifically up-regulated in psoriasis lesional skin (ARH3) or down-regulated (NUDT16 and ENPP1)." (PMID 34748530, 2021).
Right ventricular hypertrophy (1 paper, 2024). In this case the right ventricle is more muscular than normal, causing a characteristic boot-shaped (coeur-en-sabot) appearance as seen on anterior- posterior chest x-rays. "In the present study, we report a novel homozygous splice-site variant in ENPP1 (NG_008206.1(NM_006208.3):c.2230 + 5G > A), in a Pakistani patient diagnosed with severe valvular pulmonary stenosis (PS) and mild right ventricular hypertrophy (RVH)." (PMID 39538190, 2024). "In this study, we report a novel homozygous splice-site pathogenic variant in ENPP1 (NM_006208, c.2230 + 5G > A; p.Asp701Asnfs*2) residing in C-terminal nuclease-like domain (NLD) of ENPP1 protein in a Pakistani family diagnosed with severe valvular PS and mild right ventricular hypertrophy (RVH)." (PMID 39538190, 2024).
tuberculosis (1 paper, 2024). A chronic, recurrent infection caused by the bacterium Mycobacterium tuberculosis. "We hypothesized that small molecule inhibitors of bacterial and host cyclic dinucleotide PDEs, namely CdnP and the endogenous host PDE, ENPP1, might potentiate the STING pathway and act as host-directed therapies (HDTs) for tuberculosis." (PMID 38095464, 2024).